IRF1 (interferon regulatory factor 1)
Diseases named in the same sentence as IRF1 in open-access papers (continued):
Sharing a sentence is not in itself a finding about the gene and the disease.
tumor (continued). "In accordance with such a connection, IFNG mRNA in OC tumor tissue, intratumoral interferon regulatory factor (IRF)‐1 and genes linked to IFN signaling have been associated with a favorable clinical outcome." (PMID 35451191, 2022). "In parallel, multiple studies found IRF1 to be associated with tumor suppression, natural killer (NK) and T cell development, and B cell biology, changing the focus of the field." (PMID 33476326, 2021). "Whereas BCA2 activates IRF1 in HEK293T and MCF-7 (ER+) cells, it causes IRF1 down-regulation in ER– and non-tumor breast cell lines." (PMID 34589482, 2021). "The expression of CD3D, CD3G, CXCL9, and IRF1 were significantly associated with tumor stage and distant metastasis." (PMID 32925784, 2020). "IRF1 is a member of the interferon regulatory factor family; the protein encoded by this gene is considered a tumor suppressor by stimulating the immune response against tumors." (PMID 32925784, 2020). "This suggests that partial or complete loss of IRF1 expression alters the type, number, and function of immune cells in situ during chronic inflammation, possibly via the creation of a tumor-promoting environment." (PMID 31827213, 2019). "In order to verify that the upregulation of PD-L1 on Stat1 deficient macrophages, increased IL-10 secretion and impaired Irf1 expression also impairs the killing function of Stat1 deficient macrophages, we next isolated CD11b+ cells from tumor bearing lungs." (PMID 30647851, 2018). "This mutation attenuates the transcriptional activity of IRF-1 and consequently, its tumor-suppressing capability is lost." (PMID 29599126, 2018). "This alteration was accompanied by loss of IRF-1 transcriptional and, consequently, tumor-suppressing activity." (PMID 29599126, 2018). "In cancer patients, the expression level of IRF1 mRNA is negatively correlated with the tumor grade, risk of recurrence and death." (PMID 27508303, 2016). "For example, anti-tumor function of IRF-1- and IRF-5-associated pathways have been suggested in CRC." (PMID 27092172, 2016). "The discussed observations demonstrate that tumor surveillance by the immune system is impaired by loss of IRF-1." (PMID 23420765, 2013). "The role of IRF-1 in the regulation of various types of human tumor has important implications for understanding the susceptibility and progression of cancer." (PMID 23420765, 2013). "Irf1 expression by tumor cells was associated with an increased CXCL11/CXCR3-dependent NK cell infiltration of lung nodules." (PMID 23269924, 2012). "Several studies emphasized on IRF-1 as a transcriptional activator that facilitates a Th1 immune phenotype and leads to tumor infiltration of CD8+ lymphocytes associated with a favorable prognosis in cancer patients." (PMID 21875439, 2011). "In the context of endocrine responsive breast cancers, it is important to understand the underlying mechanism that IRF1 uses to mediate tumor suppressive activity." (PMID 22295238, 2011). "IRF1 encodes a transcription factor stimulates an immune response against tumor cells and FAM3B encodes a protein called FAM3B/PANDER, which is a hormone that regulates glucose and lipid metabolism and its expression is associated with the progression of multiple types of cancer." (PMID 40110195, 2025). "Additionally, SPOP mutations have been implicated in tumor immune escape by regulating the IRF1-PD-L1 axis, further highlighting its critical role in immune modulation." (PMID 40657370, 2025). "Concurrently, IFNγ can upregulate Acyl-CoA Synthetase Long Chain Family Member 4 expression through STAT1/IRF1 signaling, facilitating the integration of tumor microenvironment-associated arachidonic acid into phospholipids, inducing ferroptosis in tumor cells." (PMID 40136510, 2025). "Prior work suggests uptake of apoptotic cells may drive CCR7‐associated cDC1 activation programmes, while IRF1 and NF‐κB pathways have been more generally linked to cDC1 activation in tumours." (PMID 40745918, 2025).
tumor (continued). "Notably, high levels of IRF1 expression in glioblastoma are associated with tumor progression and poor prognosis." (PMID 40025540, 2025). "In contrast to that observed for MHV68 orf36, global deficiency of Interferon Regulatory Factor 1 (IRF-1), a tumor suppressor and a founding member of the IRF family, led to an exaggerated germinal center response driven by chronic infection with MHV68, but not LCMV." (PMID 41263556, 2025). "IRF1 has also been associated with tumor response to chemotherapy and radiotherapy." (PMID 38396830, 2024). "Loss of IRF1 in tumor cells suppressed PD-L1 and sensitized T cells to the immune response." (PMID 38396830, 2024). "In addition, the mechanisms associated with IFNγ-mediated upregulation of IRF1 and PD-L1, which triggers tumor evasion of T cell immunity, are also present in tumor-infiltrating myeloid-derived suppressor cells (MDSCs)." (PMID 38396830, 2024). "Furthermore, we demonstrated that TAK1/NF-κB/IRF1 signaling was also activated in cDC1 from TdLNs of MC38 tumor-bearing Bcl9/Bcl9l deficiency mice using multiplex immunofluorescence." (PMID 38811552, 2024). "As a well-know tumor suppressor gene, functionally inactivating point mutation of IRF1 was reported in GC, high frequency of loss of heterozygosity of the IRF1 locus on chromosome 5q has been frequently observed in GC, suggesting that IRF1 plays an important role in the pathology of GC." (PMID 38448411, 2024). "The protein encoded by the IRF1 gene is a transcriptional regulator and tumor suppressor." (PMID 39051372, 2024). "Elevated levels of IRF1 in cells under different conditions may be associated with both tumor progression and inhibition of tumor growth." (PMID 38396830, 2024). "Moreover, IRF1 is a critical tumor suppressor, which is underpinned by the observation that IRF1 is mutated or lost in many cancers." (PMID 37622993, 2023). "Additionally, IRF1 has also been implicated in the regulation of CD8+ T-cell infiltration in tumours by mediating the expression of the chemokine CXCL10." (PMID 36010935, 2022). "In PC, IRF1 has been identified as an anti-oncoprotein and its overexpression has been associated with better clinic-pathological features, such as tumor differentiation, infiltration depth, tumor size, and survival time." (PMID 34462421, 2021). "The rise of the ROS levels in the TME causes the activation of the interferon regulatory factor 1 (IRF1) in tumor cells and may promote COX-2 activity and PGE2 synthesis." (PMID 34178680, 2021). "IRF1 is a tumor-suppressor gene that is associated with RCC." (PMID 34445498, 2021). "Remarkably these lines were resistant to the effects of IRF1 expression, suggesting loss of Fbxw7 function may render cancers resistant to some of the tumour suppressor activities of IRF1." (PMID 30854564, 2019). "Furthermore, XAF1 inhibits growth, migration, and invasion of tumor cells and suppresses in vivo tumor growth in a highly IRF-1-dependent manner, indicating that the tumor suppressive role of XAF1 is tightly linked to its ability to bind and activate IRF-1." (PMID 30042418, 2018). "In conclusion, IRF-1 operates as a tumor suppressor whose loss, in combination with other genetic alterations, may significantly increase risk of malignancy." (PMID 29599126, 2018). "Notably, NO productionand tumor lysis were abolished in co-cultures with macrophages deficient inInterferon Regulatory Factor, IRF-1." (PMID 25659093, 2015). "Further studies in IRF1 −/− mice demonstrated that IRF1 is a tumor susceptibility gene." (PMID 25893139, 2013). "Therefore, IRF-1 belongs to a class of tumor susceptibility genes whose loss in combination with other genetic alterations significantly increases the incidence of developing tumors." (PMID 23420765, 2013). "However, the mechanisms underlying IRF-1-mediated tumor suppression and oncogenesis remain undefined." (PMID 23420765, 2013). "In our study, high levels of IRF1 activation may be associated with an early tumor immune response." (PMID 39895784, 2025).
tumor (continued). "Reports of downregulation of IRF1 in endometrial tumorigenesis are common; however, derepression of IRF1 may occur in a subset of tumors, an event which is associated with thymidine phosphorylase upregulation and aggressive tumor behavior." (PMID 35993041, 2022). "Furthermore, our RNA-seq studies show that loss of Irf1 causes basal alterations in colonic immune and epithelial transcriptional programs, which may promote a “tumor-permissive” microenvironment." (PMID 31827213, 2019). "Altering TAM mitochondrial dynamics impacts tumor biology: fusion suppresses M1-TAM polarization by inhibiting IRF1-mediated IL-12 production, while fragmentation activates downstream IRF1 through Parkin-dependent CHIP proteolysis." (PMID 41328341, 2026). "Recent studies indicate that IRF1 is involved in cell proliferation, apoptosis, and is associated with EMT, invasion and migration in tumor cells." (PMID 41280905, 2025). "In hepatocellular carcinoma and colon cancer, IRF1 has been shown to suppress the T-cell immune response and facilitate tumor immune escape by directly binding to the promoter of the programmed death ligand 1 (PD-L1) gene, thereby enhancing its transcription." (PMID 40025540, 2025). "In particular, IRF1 can activate genes involved in innate and acquired immune responses as a TF and tumor suppressor." (PMID 40225569, 2025). "In the second part of the paper, we summarize the role that IRF-1 plays in promoting the progression of gastrointestinal tumors by helping the tumor undergo immune escape." (PMID 40909948, 2025). "DC maturation involves complex processes for efficient tumor antigen handling, regulated by interferon regulatory factor 1 (IRF-1)." (PMID 40313957, 2025). "HE staining analysis of mouse liver, spleen, and bone marrow indicated a significant reduction in tumor cells within the IRF1 knockdown group." (PMID 40025540, 2025). "Specifically, IFN-γ activates the JAK/STAT1/interferon regulatory factor 1 (IRF1) signaling pathway to upregulate ACSL4 transcription in tumor cells by promoting IRF1 binding to ACSL4 promoter region IFN-stimulated response elements." (PMID 40169575, 2025). "Bioluminescence imaging of mouse liver, spleen, and bone marrow samples revealed substantial decreases in tumor burden following IRF1 downregulation." (PMID 40025540, 2025). "The bioluminescence flux histograms of mice injected with either MV4-11 or Kasumi-1 cells consistently demonstrated that the tumor burden in the sh-IRF1 group was significantly lower compared to that in the sh-NC group." (PMID 40025540, 2025). "Collectively, these findings provide the first evidence that IGF2BP1 inhibition enhances immune checkpoint therapy by disrupting IGF2BP1-driven uncoupling of IRF1-dependent MHC-I/PD-L1 synthesis in tumor cells." (PMID 41444249, 2025). "Cheng and colleagues discovered in 2020 that the transcription factor Interferon Regulatory Factor 1 (IRF1) acts as a tumor suppressor in an AR-mediated transcriptional regulatory network in PC." (PMID 40001606, 2025). "At the same time, related studies have also confirmed the role of IRF-1 in inhibiting tumor progression by inducing apoptosis of tumor cells and activating autophagy." (PMID 40909948, 2025). "Tumor cells in high entropy MRs were also significantly more likely to have nuclear IRF1 (interferon regulatory transcription factor 1), suggesting that they were exposed to interferon-γ (IFNγ)." (PMID 40667360, 2025). "The study by experienced pathologists involved determining the percentage of IRF1-positive tumor cells and evaluating the histochemical score." (PMID 39897128, 2025).
tumor (continued). "Upon CD8+ T cell activation, released IFN-γ binds its receptors and activates the JAK/STAT signaling pathway, leading to IRF-1 activation and induction of PD-L1 expression on tumor cells, as reported in various human cancer models." (PMID 41463161, 2025). "Numerous investigations into gastrointestinal tumors have revealed that IRF-1 exhibits a ‘double-edged sword’ role, simultaneously promoting and inhibiting tumor progression by regulating various downstream factors mediated by the IFN-γ/STAT1 pathway." (PMID 40909948, 2025). "Among these, IRF1 exerts its tumor-suppressive effects by promoting ferroptosis and apoptosis, thereby inducing tumor cell death." (PMID 40740774, 2025). "Activation of the IFN-γ/STAT1 signaling promotes the transcription of IRF-1, upregulating PD-L1 expression in tumor cells." (PMID 40909948, 2025). "Results showed that upon cytokine stimulation most of the studied genes were expressed at a lower level in the tumor cells than in control cells, such as Stat1, Irf1, Cxcl9, Cxcl10, IκBα, and Bcl2 (p< 0.05)." (PMID 40287766, 2025). "Analysis of the GEPIA dataset demonstrated that IRF1 exhibited higher median expression levels in AML compared to other tumor types, with elevated expression levels observed in cancer cells compared to normal cells." (PMID 40025540, 2025). "Arachidonic acid and IFN-γ facilitate the upregulation of ACSL4 expression by activating the STAT1 and IRF1 signaling pathways, ultimately leading to ferroptosis induction in tumor cells." (PMID 40140647, 2025). "Specifically, exosomal miR-21 has been experimentally shown to promote macrophage M2 polarization and tumour progression in NSCLC by targeting IRF1 under hypoxic conditions." (PMID 41311647, 2025). "Together, our analysis indicated higher IRF1 expression in tumor segments in “hot” ROIs and a correlation between IRF1 signaling and CYT scores across MRTs." (PMID 40894019, 2025). "Despite many studies indicating the antitumor effect of IRF1, it has also been shown to promote tumor growth and progression (right side)." (PMID 38396830, 2024). "It appears that the intrinsic effects of the IRF1 protein on carcinogenesis and tumor growth are as ambivalent as the known functions of the IFNγ signaling pathway itself." (PMID 38396830, 2024). "As a well-known tumor suppressor, IRF1 exerts multiple biological functions in cancer cells, including antiproliferation, initiation of apoptosis and cell cycle arrest." (PMID 38448411, 2024). "As a well-known tumor suppressor gene, IRF1 was reported to regulate cancer progression via suppressing proliferation and epithelial-mesenchymal transition, inducing apoptosis of cancer cells." (PMID 38448411, 2024). "FOXO1 functioned as a tumor suppressor by promoting macrophage infiltration and antitumor polarization via positive regulation of the IRF1/NO pathway." (PMID 38999981, 2024). "IGF2BP3 regulates the stability and translation of NFAT1 mRNA in a m6A-dependent manner, and NFAT1 negatively mediates tumor suppressor IRF1 expression through regulating its transcription." (PMID 38448411, 2024). "In two murine tumor xenografts, combination therapy of CGA with anti-PD-1 antibody decreased the expression of PD-L1 and IRF1 and increased the inhibitory effect of the anti-PD-1 antibody on tumor growth." (PMID 38164171, 2024). "IRF1 is the earliest interferon regulatory factor, and its expression regulates the malignant biological behavior of tumor cells, IRF1 inactivation increases the risk of tumorigenesis." (PMID 38915471, 2024). "Supplementation of 4-OI in IRF1 KO cells rescued thimerosal-induced tumor immunogenicity, indicating that defective itaconate production is responsible for the impaired immunogenicity of IRF1 KO cells." (PMID 39349845, 2024).
tumor (continued). "Intriguingly, cluster 6, which exhibited moderate differentiation state, was found highest expression level of transcription factors STAT1/STAT2-IRF9/IRF1 activated by interferon gamma (IFN-γ) leading to upregulation of tumor PD-L1 expression following RT." (PMID 38528587, 2024). "Myeloid subclusters 1 (recruited monocytes) and 2 (dendritic cells) were characterised by IRF1 transcription factor activity, a promoter of anti‐tumour immunity in conventional dendritic cells." (PMID 38426634, 2024). "Western blot results showed that the protein levels of SRC‐1, IRF1, and PD‐L1 in tumor tissues of most patients were higher than those of paracancerous tissues." (PMID 38953362, 2024). "Consistent with our previous research, we observed a significant upregulation of PROS1 in MICA+ and IRF1+ tumor cells." (PMID 38254761, 2024). "Overall, IRF1 expression is beneficial for inhibiting the growth of GC cells through inducing tumor cell apoptosis, enhancing sensitivity to chemotherapy drugs, and suppressing the miR-18a/19a and Wnt/β-catenin pathways." (PMID 39384770, 2024). "To investigate this, we assessed the expression of Rel, Relb and Irf1 of cDC1 in TdLNs and tumors from B16-OVA tumor-bearing Bcl9/Bcl9l deficiency mice using SCENIC analysis." (PMID 38811552, 2024). "IRF1 has been shown to affect several important antitumor mechanisms, such as induction of apoptosis, cell cycle arrest, remodeling of tumor immune microenvironment, suppression of telomerase activity, suppression of angiogenesis and others." (PMID 38396830, 2024). "STXBP6-dependent cytoplasmic retention of IRF1 then resulted in reduced PD-L1 levels, improved T cell antitumor immune response, and reduced tumor mass." (PMID 38396830, 2024). "IRF1 is known to have multiple roles, including resisting infection, inhibiting tumours, suppressing proliferation and promoting apoptosis." (PMID 39730319, 2024). "Several antigen presentation genes, such as Tap1 and CD74 and some regulators involved in tumor cell immunogenicity, such as Irf1, Icam1 and CD40 were also upregulated by Mi-2β knockout in vitro." (PMID 38461299, 2024). "High CD8+ T cells infiltration was correlated with increased IRF1 expression in the nucleus of tumor cells and better short-term outcomes, and there was a positive association between the expression of PD‐L1 and IRF1 in tumor cells." (PMID 38654284, 2024). "IRF1 is a regulator of diverse cellular functions and a known tumor suppressor whose endocrine responsiveness regulates cell fate in cancers." (PMID 38339304, 2024). "More interestingly, one gene—IRF1 (interferon regulatory factor 1)—was common to both pathways (and to both bulk tumor models) and selected in four out of five modules being downregulated in the early relapse group." (PMID 38706608, 2024). "This review will focus on the established tumor-suppressive and tumor-promoting functions of IRF1, as well as the molecular mechanisms of IRF1 regulation identified in various cancers." (PMID 38396830, 2024). "IHC results showed that IGF2BP3 knockdown led to a lower level of NFAT1 and higher level of IRF1 in xenograft tumor tissues." (PMID 38448411, 2024). "Conversely, miR-345 showed low expression in HCC, counteracting the inhibitory impact of IRF1 through reversible trans-overexpression, thereby influencing the epithelial-mesenchymal transition process and tumor metastasis." (PMID 38999981, 2024). "The role of IRF1 in inducing epithelial–mesenchymal transition (EMT) in tumor cells has also been reported." (PMID 38396830, 2024). "CsnB enhances Nur77-mediated tumor inhibition by downregulating IRF1 expression, and pharmacological Nur77 stimulation with CsnB significantly enhances anti-PD-1 immunotherapy efficacy in a mouse tumor model." (PMID 38789431, 2024). "In this case, CDK2 and IRF1 being in the active state were the largest contributors to correctly identifying the cell state of the tumor as NPC." (PMID 38766170, 2024).